DCTN2 (dynactin subunit 2)
Description:
Part of the dynactin complex that activates the molecular motor dynein for ultra-processive transport along microtubules. In the dynactin soulder domain, binds the ACTR1A filament and acts as a molecular ruler to determine the length (By similarity). Modulates cytoplasmic dynein binding to an organelle, and plays a role in prometaphase chromosome alignment and spindle organization during mitosis. Involved in anchoring microtubules to centrosomes. May play a role in synapse formation during brain development (By similarity).
Synonyms: DCTN-50; DCTN50; RBP50; DYNAMITIN; HEL-S-77
Tractability: Antibody: UniProt places it where antibodies can reach, with high confidence. PROTAC: ubiquitination databases record sites on it; its protein half-life has been measured.
Gene: Protein-coding gene on chromosome 12 (57,529,633 to 57,547,242, reverse strand). Ensembl gene ENSG00000175203.
Subcellular location: Cytoplasm, cytoskeleton, microtubule organizing center, centrosome; Membrane; Cytoplasm, cytoskeleton
Subcellular location (Human Protein Atlas): Basal body; Centrosome; Connecting piece; Cytosol; End piece; Mid piece; Principal piece
Pathways (Reactome):
Cell Cycle: AURKA Activation by TPX2; Loss of Nlp from mitotic centrosomes; Loss of proteins required for interphase microtubule organization from the centrosome; Recruitment of NuMA to mitotic centrosomes; Recruitment of mitotic centrosome proteins and complexes; Regulation of PLK1 Activity at G2/M Transition
Vesicle-mediated transport: COPI-independent Golgi-to-ER retrograde traffic; COPI-mediated anterograde transport
Cellular responses to stimuli: HSP90 chaperone cycle for steroid hormone receptors (SHR) in the presence of ligand
Immune System: MHC class II antigen presentation
Organelle biogenesis and maintenance: Anchoring of the basal body to the plasma membrane
Gene Ontology:
Molecular function: identical protein binding; protein binding; protein kinase binding; spectrin binding
Biological process: mitotic metaphase chromosome alignment; mitotic spindle organization; protein localization to centrosome; microtubule-based process
Cellular component: centrosome; ciliary basal body; dynactin complex; extracellular exosome; kinetochore; vesicle; cytoplasm; cytosol; cytoskeleton; growth cone; membrane
Genetic constraint (gnomAD): Loss-of-function variants: 18 observed, 49.46 expected, observed/expected ratio (o/e) 0.36, 90% interval 0.25 to 0.54. The upper end of that interval is the gene's LOEUF score, 0.54, which puts it in group 2 of 6, group 1 being the genes least tolerant of losing a copy. Missense variants: 390 observed, 476.17 expected, observed/expected ratio (o/e) 0.82, 90% interval 0.75 to 0.89. Synonymous variants: 168 observed, 176.35 expected, observed/expected ratio (o/e) 0.95, 90% interval 0.84 to 1.08.
Homologues: Orthologues: chimpanzee DCTN2 (99% identical), macaque DCTN2 (99% identical), pig DCTN2 (97% identical), rabbit DCTN2 (97% identical), dog DCTN2 (97% identical), rat Dctn2 (96% identical), mouse Dctn2 (96% identical), guinea pig DCTN2 (95% identical), tropical clawed frog dctn2 (80% identical), zebrafish dctn2 (71% identical), Drosophila melanogaster DCTN2-p50 (32% identical), Caenorhabditis elegans dnc-2 (21% identical).
Diseases named in the same sentence as DCTN2 in open-access papers:
DCTN2 is named in the same sentence as 21 diseases in open-access papers, as found by Europe PMC text mining. Sharing a sentence is not in itself a finding about the gene and the disease. The quoted sentences say what the papers report.
hepatocellular carcinoma (4 papers, 2024 to 2025). A malignant tumor that arises from hepatocytes. "Dynactin (DCTN) proteins are involved in intracellular transport, and high levels of DCTN2 are associated with a poor prognosis in hepatocellular carcinoma." (PMID 39739031, 2025). "For instance, DCTN2 plays a vital role in mitotic spindle assembly and has been implicated in hepatocellular carcinoma via the AKT pathway." (PMID 40861419, 2025). "More importantly, we elucidated the functional impact of DCTN2 on hepatocellular carcinoma (HCC) progression and its underlying mechanisms." (PMID 38842133, 2024).
bladder cancer (2 papers, 2024 to 2025). "The results of the survival analysis demonstrated that increased expression of DCTN2 was linked to reduced overall survival rates across multiple cancer types, such as bladder cancer, kidney renal clear cell carcinoma and liver hepatocellular carcinoma (LIHC)." (PMID 38842133, 2024).
breast carcinoma (2 papers, 2021 to 2024). "In conclusion, we identified and constructed a 5-gene signature (GP6, MAK, DCTN2, TMEM156, and FKBP14) prognostic model to predict prognosis in breast cancer patients." (PMID 34722557, 2021). "The results indicated that DCTN2 expression was dysregulated in most tumours, with elevated expression in many type of cancers, such as HCC, glioblastoma (GBM), pancreatic cancer and decreased expression in other cancers, such as breast cancer, colocteral cancer and ovarian cancer." (PMID 38842133, 2024).
colon adenocarcinoma (2 papers, 2019 to 2021). "The DCTN family has been linked to neurodegeneration, and more and more studies have shown that DCTN2 may be a potential prognostic biomarker for cancer, including cutaneous melanoma, colon adenocarcinoma, and osteosarcoma." (PMID 34722557, 2021). "DCTN1, DCTN2, and DCTN4 could serve as biomarkers to predict the prognosis and diagnosis of colon adenocarcinoma (COAD)." (PMID 31847905, 2019).
Cholecystitis (1 paper, 2025). The presence of inflammatory changes in the gallbladder. "Notably, we identified a subset of eight plasma proteins (PAHX, CD8A, HRG, CRIS2, Dynactin subunit 2, AT2A3, CSTN2, and DEPP) that effectively differentiated GBC from cholecystitis with a diagnostic accuracy of 94% when validated on a test set." (PMID 40470116, 2025).
liver cancer (1 paper, 2024). An epithelial or non-epithelial malignant neoplasm that arises from the liver. "DCTN2 significantly correlated with neutrophils, macrophages, and cancer‐associated fibroblasts (CAFs) in most types of cancer, including liver cancer, thyroid cancer, ovarian cancer, and stomach carcinoma." (PMID 38842133, 2024).
motor neuron disease (1 paper, 2021). "Moreover, dynactin (Dctn1) acting with overexpressed dynamitin (Dctn2), was shown to produce a late-onset progressive motor neuron disease inhibiting axonal transport in transgenic mice." (PMID 34946792, 2021).
type 1 diabetes mellitus (1 paper, 2022). A chronic condition characterized by minimal or absent production of insulin by the pancreas. "Suppression of AMFR and DCTN2 expression is expected to enhance the efficacy of stem cell transplantation in patients with type 1 diabetes." (PMID 36267277, 2022). "This study was the first report, characterized stem cells from a patient with type 1 diabetes and demonstrated the efficacy of AMFR and DCTN2 in stem cell transplantation." (PMID 36267277, 2022).
cancer (6 papers, 2008 to 2024). A tumor composed of atypical neoplastic, often pleomorphic cells that invade other tissues. "DCTN2 (Dynactin subunit 2) is a protein that has been linked to cancer and was identified in the pancreata of wild-type mice." (PMID 39125590, 2024). "Although several studies have suggested that abnormal expression of DCTN2 may be associated with tumorigenesis and tumour progression the exact role of DCTN2 in various cancers is not yet fully understood, and its potential connection with antitumor immune responses warrants further investigation." (PMID 38842133, 2024). "We first utilized Tumour Immune Estimation Resource (TIMER) online analysis database to delve the expression status of DCTN2 in various cancers." (PMID 38842133, 2024). "This study offers valuable insights into the significance of DCTN2 in diverse types of cancers, highlighting the promising therapeutic potential of targeting DCTN2 in the treatment of HCC." (PMID 38842133, 2024). "In this study, we performed a thorough pan‐cancer analysis to examine the molecular features and prognostic implications of DCTN2 using data from multiple databases." (PMID 38842133, 2024). "To investigate the molecular mechanisms by which DCTN2 exerts the tumour‐promoting effects, we examined the AKT pathway, a well‐known signalling pathway implicated in cancer progression." (PMID 38842133, 2024). "These cells have been demonstrated to promote immunosuppressive microenvironment formation and tumour progression, indicating that DCTN2 plays an immunosuppressive role in various cancers." (PMID 38842133, 2024). "Further exploration is warranted to understand the complex interplay between DCTN2 and the immune microenvironment in cancer." (PMID 38842133, 2024). "In this study, we examined DCTN2 expression in a pan‐cancer setting." (PMID 38842133, 2024). "Therefore, the objective of this study was to comprehensively investigate the expression status and potential function of DCTN2 in various malignancies through different database, such as The Cancer Genome Atlas, the Genotype‐Tissue Expression and Gene Expression Omnimus databases." (PMID 38842133, 2024). "Dynactin subunit 2 (DCTN2) has been reported to play a role in progression of several tumours; however, the involvement of DCTN2 in potential mechanism or the tumour immune microenvironment among various cancers still remains largely unknown." (PMID 38842133, 2024). "The survival analysis indicated that DCTN2 overexpression had a negative prognostic impact on the clinical outcomes of patients with cancer." (PMID 38842133, 2024).
tumor (5 papers, 2016 to 2024). "Rescue experiments revealed that the anti‐tumour effects of DCTN2 knockdown were partially reversed upon AKT pathway activation." (PMID 38842133, 2024). "The top and bottom 30 percent samples, based on DCTN2 expression, were selected for each tumour type, and differential gene analysis was conducted using the limma package." (PMID 38842133, 2024). "Silencing DCTN2 dramatically suppressed the proliferative and metastasis capacities of tumour cell in vitro." (PMID 38842133, 2024). "We validated the involvement of the AKT pathway in DCTN2‐mediated tumour progression through western blot analysis, which revealed that DCTN2 inhibition led to a substantial decrease in AKT phosphorylation levels." (PMID 38842133, 2024). "AKT activation partially rescues the inhibitory effects of DCTN2 silencing on cell proliferation and invasion, suggesting that the AKT pathway plays a role in mediating the tumour‐promoting effects of DCTN2." (PMID 38842133, 2024). "We discovered that DCTN2 expression was high in many type of tumours tissues compared to adjacent non‐tumour ones." (PMID 38842133, 2024). "Contrary to the serum profile, urine from OH-BBN induced C57BL/6 mice displayed increased levels of the pro-inflammatory cytokines Ccl3 and Il1β, as well as an upregulation of tumor promoting Ppp1r2, Pak4, tumor growth marker Nadk, and Dctn2." (PMID 34232958, 2021). "The results of immunohistochemistry showed that MAK, GP6, and TEMEM156 were significantly highly expressed in tumor tissues, and DCTN2 was highly expressed in normal tissues." (PMID 34722557, 2021). "Overall, DCTN2 may be a potent biomarker signifying tumour prognosis and a promising therapeutic target for tumour treatment, particularly in HCC." (PMID 38842133, 2024). "Mechanistically, DCTN2 exerted tumour‐promoting effects by modulating the AKT signalling pathway." (PMID 38842133, 2024). "Additionally, we accessed the correlation between DCTN2 and immune biomarkers, shedding light on their relevance in the context of tumour immunity." (PMID 38842133, 2024). "High DCTN2 signified poor prognosis for patients with tumours." (PMID 38842133, 2024). "DCTN2 exhibited a predominantly high expression profile in all tumour samples from the TCGA database, which alluded to its potential role as an oncogenic driver for tumorigenesis and tumour progression." (PMID 38842133, 2024). "Moreover, rescue experiments using SC79, an AKT agonist, partially restored the proliferative and migratory abilities of HCC cells by silencing DCTN2, further supporting the involvement of the AKT pathway in DCTN2‐mediated tumour suppression." (PMID 38842133, 2024). "Moreover, paired analysis further revealed significantly higher expression of DCTN2 in many tumour tissues." (PMID 38842133, 2024). "DCTN2 expression was much higher in HCC tissues than in adjacent non‐tumour tissues." (PMID 38842133, 2024). "Furthermore, GSVA and GSEA‐HALLMARKER analyses revealed that DCTN2 was positively associated with tumour‐promoting pathways such as the PI3K/AKT/mTOR pathway, MYC_targets, and E2F_targets, indicating that DCTN2 was significantly related to various tumour‐related pathways." (PMID 38842133, 2024). "Additionally, Gene Set Enrichment Analysis (GSEA) analysis revealed that DCTN2 was positively correlated with oncogenic pathways, including cell cycle, tumour metastasis‐related pathway, while it was negatively with anti‐tumour immune signalling pathway, such as INF‐γ response." (PMID 38842133, 2024). "The analysis demonstrated a positive correlation between DCTN2 expression and cell cycle and EMT pathways in multiple tumours." (PMID 38842133, 2024).
infection (1 paper, 2024). The state of being infected such as from the introduction of a foreign agent such as serum, vaccine, antigenic substance or organism. "The experiment was performed in a similar fashion, whereby we infected the DCTN2 siRNA-treated HFF cells with GFP-Tg and counted the number of tachyzoites in each individual PV over 72 h of infection." (PMID 39769222, 2024).
DCTN2 also shares sentences with these, for which no sentence is quoted: colorectal cancer (2 papers); Alzheimer disease (1); cutaneous melanoma (1); glioblastoma (1); Hematological Disease (1); osteosarcoma (1); ovarian carcinoma (1); pancreatic cancer (1); stomach carcinoma (1); thyroid cancer (1).